PTH (parathyroid hormone)
Diseases named in the same sentence as PTH in open-access papers (continued):
Sharing a sentence is not in itself a finding about the gene and the disease.
parathyroid adenoma (continued). "The main findings of the present study were that US-guided percutaneous LA therapy in patients with primary HPT due to parathyroid adenoma resulted in significant reductions in nodule size, serum calcium concentration, and serum PTH level that were maintained for 12 months." (PMID 26788059, 2015). "Primary HPT occurs when one or more parathyroid glands secrete an excessive amount of PTH, as in the case of a parathyroid adenoma; secondary HPT results when increased secretion of PTH is a response to lowered ionized calcium, typically as a result of renal disease." (PMID 26413096, 2015). "The limitation of PTH–FNA is an undetected parathyroid adenoma on US." (PMID 25379182, 2014). "It is known that anesthetic technique influence PTH levels during the minutes following induction to anaesthesia, in that way excising a possible parathyroid adenoma too fast in a high responder, may lead to a smaller fall of PTH than expected." (PMID 24804234, 2014). "In our case, venous sampling taken at the time of the second surgical showed highest PTH in the areas of the left innominate vein and superior vena cava, coinciding with the left sided location of the occult parathyroid adenoma found on 4DCT in the mediastinum." (PMID 24381775, 2013). "GCMB gene is important for normal synthesis of parathyroid hormone in humans and could be involved in parathyroid adenoma genesis." (PMID 23148717, 2012). "All patients had elevated serum PTH concentrations due to a parathyroid adenoma." (PMID 21698093, 2011). "After surgical removal of the parathyroid adenoma, PTH levels decreased to 212 pg/ml." (PMID 20454761, 2010). "One case of a parathyroid adenoma was negative for PTH in immunohistochemistry (IHC) and produced biologically active but truncated PTH variant that could not be detected using conventional assays." (PMID 40762649, 2025). "Furthermore, it is noticed that giant parathyroid adenomas could have a lower incidence of symptoms despite increased PTH production." (PMID 39459453, 2024). "However, functional status of the parathyroid adenoma demonstrated a significant correlation with PTH/Svol, which suggests that the volume of metabolically active tissue may be a more effective marker than the simple metabolic volume." (PMID 37892003, 2023). "This suggests that parathyroid adenoma cells are less efficient at producing PTH relative to normal parathyroid cells; hence the higher levels of serum PTH in individuals with parathyroid adenoma may simply reflect that these tumors contain more cells that produce PTH than normal parathyroid tissue." (PMID 30832348, 2019). "Also, serum PTH level correlated directly with parathyroid adenoma weight (ρ = 0.77; p < 0.0001)." (PMID 28600574, 2017). "Prospective study of patients who underwent parathyroid adenoma excision by PHPT, collected right and left internal jugular vein blood sample for analysis of Parathyroid Hormone." (PMID 40209343, 2025). "In the normocalcaemic group, the cause of elevated PTH was not identified in the majority of patients (108/110, 98.2%) as patients with known secondary causes had been excluded from this study; two patients had parathyroid adenomas localised on sestamibi scans." (PMID 40608198, 2025). "Between January 2022 and August 2024, data from 128 parathyroid adenomas in 122 patients who were prepared for surgery due to PHPT and underwent ultrasound-guided FNAB along with PTH-WO testing were retrospectively evaluated." (PMID 41036141, 2025). "Preoperative and postoperative serum parathyroid hormone (PTH), calcium and 25-hydroxyvitamin D levels and pathological size of the parathyroid adenoma were recorded." (PMID 40979160, 2025). "CYP24 inhibits PTH secretion by repressing PTH transcription, and CYP24 is downregulated in MEN1 mutant parathyroid adenomas." (PMID 39336822, 2024).
parathyroid adenoma (continued). "Based on these exams, it was determined that the patient had a parathyroid adenoma, which was responsible for PHPT characterised by increased levels of calcium, phosphate, and PTH." (PMID 38721190, 2024). "Further investigations revealed an elevated parathyroid hormone (PTH) and an ultrasound of the thyroid revealed parathyroid adenoma." (PMID 37719553, 2023). "Increased level of parathyroid hormone (PTH) was confirmed by laboratory tests, and imaging examination showed multiple parathyroid adenomas." (PMID 35370956, 2022). "Owing to the increase in PTH levels and parathyroid function, ultrasonography and 99mTc-MIBI scintigraphy facilitate the diagnosis of giant parathyroid adenoma." (PMID 35414046, 2022). "Parathyroid hormone (PTH), a polypeptide hormone, has been shown to form amyloid and amyloid-like beta-sheet aggregation in parathyroid adenomas." (PMID 36704039, 2022). "One of our cases (case 2) presented with normal Ca and high PTH levels but displayed typical features of PHPT including a raised CCCR and renal calculi, and the presence of a parathyroid adenoma identified both by ultrasound scan and 99mTc-sestamibi-SPECT/CT." (PMID 31797261, 2020). "Surgical removal of parathyroid adenomas, responsible for PHPT is the treatment of choice for restoring normal PTH secretion and serum level of calcium; parathyroidectomy demonstrated to normalize bone and mineral metabolism parameters." (PMID 32326947, 2020). "The patient was evaluated for weakness and elevated serum level of Ca and PTH in laboratory data, the parathyroid scintigraphy with 99mTc-MIBI revealed a left parathyroid adenoma." (PMID 30317121, 2018). "In a small fraction of parathyroid adenomas, overexpression is due to activation of the CCND1 gene by pericentromeric inversions of Chromosome 11, involving the parathyroid hormone (PTH) promoter." (PMID 18044981, 2007). "Selective parathyroidectomy produced a rapid intraoperative PTH decline, and pathology supported parathyroid adenoma rather than carcinoma." (PMID 41899334, 2026). "In contrast, other authors have studied the chief cells and oxyphilic cells within parathyroid adenomas from a molecular perspective, without confirming a proportional relationship between the number of chief cells and calcium or PTH levels." (PMID 39883321, 2025). "There was a significant difference between patients with and without parathyroid adenoma regarding serum preoperative Ca, P, and PTH levels (p < 0.00)." (PMID 40104303, 2025). "Given the aggressiveness of osteoporosis-related bone traumata and the high level of preoperative hypercalcemia and PTH, which is not common in patients with parathyroid adenomas, the patient was then diagnosed with suspected PC." (PMID 40026929, 2025). "The results of this study suggested a positive correlation between the volume of the parathyroid adenoma and preoperative PTH and calcium levels, while a negative correlation was seen with phosphate and Vitamin D." (PMID 39883321, 2025). "PHPT is characterized by autonomous secretion of parathyroid hormone (PTH) by parathyroid tissues, and about 80-85% of cases originate from monoclonal parathyroid adenomas, the molecular mechanism of which involves cyclin D1 (CCND1/PRAD1) overexpression and the development of Wnt/β-cyclin." (PMID 41210508, 2025). "The patient underwent surgical excision of the left parathyroid adenoma by cervicotomy and thyroid lobe preservation with prompt normal PTH level recovery without complications." (PMID 39712793, 2024). "It has been proposed that over secretion of PTH in patients with PHPT is, among others, produced by an alteration of the CaSR set-point, being the immunohistochemical expression of the CaSR and CaSR mRNA expression reduced in parathyroid adenomas." (PMID 38214877, 2024).
parathyroid adenoma (continued). "In control experiments, immunohistochemical staining revealed intense PTH staining in chief cells of the de-identified parathyroid adenoma, with negative immunoreactivity observed in endothelial cells (marked with arrowheads)." (PMID 38554052, 2024). "The parathyroid glands are composed of PTH-secreting master cells, nonfunctional eosinophils, and clear cells, whereas parathyroid adenomas are mostly composed of principal cells." (PMID 37113486, 2023). "Consistent with earlier studies, we found that PTH transcript abundance was not elevated in parathyroid adenomas relative to normal tissue, suggesting that the hypersecretory behavior of these tumors is not dependent upon increased PTH gene expression." (PMID 36992820, 2023). "The one case showed a temporary decline in total serum calcium and PTH levels after resection but inclined again shortly afterwards, most likely due to a second, contralateral parathyroid adenoma that was not depicted by the PET/CT image." (PMID 35629070, 2022). "In 8 out of 9 (89%) cases in which PTH excess could be attributed to a specific site by SPVS, the presence of the parathyroid adenoma was confirmed intraoperatively." (PMID 33993327, 2021). "A previous study showed that MIBI-negative parathyroid adenoma only present in patients with PTH values below 150 pg/ml, which indicated the influence of serum PTH on the sensitivity of 99mTc-MIBI SPECT/CT." (PMID 34840566, 2021). "The workup showed no signs of parathyroid adenomas, but the metastasis produced intact parathyroid hormone." (PMID 33413267, 2021). "In cases of failure or discordant results, selective parathyroid hormone venous sampling (SPVS) is a method with the potential to regionalize or lateralize a parathyroid adenoma without giving the exact position and relation to other structures." (PMID 33993327, 2021). "Neck ultrasound, sestamibi scintigraphy, C11-methionine PET-CT, and selective parathyroid hormone venous sampling, but not MRI imaging, effectively detected the presence of a parathyroid adenoma with high positive predictive values." (PMID 33993327, 2021). "In two patients, no parathyroid adenoma was found intraoperatively, both with a negative scan, and in one patient, a parathyroid adenoma was removed but elevated PTH persisted during follow-up." (PMID 31367807, 2019). "PC, parathyroid adenoma (PA), and atypical parathyroid adenoma (APA) cannot be reliably distinguished on the basis of plasma concentrations of calcium and PTH in individual patients, although plasma calcium and PTH concentrations are often higher in patients with PC than patients with PA." (PMID 28881068, 2017). "It was noted that the highest level of serum parathyroid hormone detected was 2490 pg/mL and was found in patient with parathyroid adenoma not carcinoma." (PMID 22701120, 2012). "Markedly elevated serum calcium and PTH: Serum calcium levels are within 1 mg/dl above the upper normal limit in most patients with parathyroid adenomas and >14–15 mg/dl in most patients with parathyroid carcinoma." (PMID 19016595, 2008). "Therefore, we conclude that in orthotopic parathyroid adenomas, PTH-WO levels are independent of anatomical location and embryological origin." (PMID 41036141, 2025). "In conclusion, this case raises the intriguing question of whether elevated PTH levels are an absolute requirement for the diagnosis of parathyroid adenomas, as evidently this is not always the case." (PMID 40821457, 2025). "Also in our study, patients with nonfunctioning PC have an average PTH level of 173.5 pg/ml (2.5 times of normal range), which is higher than patients with parathyroid adenoma." (PMID 36193301, 2022). "Despite giant parathyroid adenomas and high parathyroid hormone levels, a calcium crisis may not always occur in these patients, and the masses may be initially misdiagnosed as a thyroid mass." (PMID 35414046, 2022).
parathyroid adenoma (continued). "Oncocytic parathyroid tumors are functional but may not have as elevated serum calcium or parathyroid hormone levels as comparable conventional parathyroid adenomas." (PMID 33269427, 2021). "Moreover, as intraoperative frozen section analyses not always are effective in distinguishing single parathyroid adenomas from multiglandular involvement, intraoperative PTH assays are probably more reliable in this context." (PMID 33269427, 2021). "The findings were similar to ours with normal PTH levels and no sign of parathyroid adenoma." (PMID 23819070, 2013). "Important to exclude in the differential diagnosis are intrathyroidal parathyroid adenoma, follicular thyroid carcinoma (TTF-1 and thyroglobulin positive, PTH negative), and medullary thyroid carcinoma (TTF-1 and calcitonin positive, thyroglobulin and PTH negative)." (PMID 23936709, 2013).
Hypercalciuria (197 papers, 2006 to 2026). "In a few cases of renal Ca leak hypercalciuria, there is an obligatory loss of Ca in the urine, which can lead to hypocalcemia and increased PTH levels." (PMID 40416164, 2025). "On the other hand, the virtual Hypercalciuria/Hyper-PTH panel uncovered only the TRPV5 variant, but this variant being not unique to the proband, cannot explain his severe skeletal phenotype." (PMID 38528055, 2024). "Calcium repletion targets the low-normal range, as PTH deficiency causes hypercalciuria with a high risk of nephrolithiasis." (PMID 39049863, 2024). "In conclusion, in postmenopausal osteoporotic women, hypercalciuria is associated with kidney stones in about one-third of patients and with a wide range of impaired PTH secretion, determining a diagnostic challenge." (PMID 34977081, 2021). "PTH was the main determinant of the mineral metabolic profile associated with hypercalciuria and reduced bone mineral density." (PMID 34977081, 2021). "Results from this study can be used to establish adequate sample size calculations in an effort to explore associations between PTH and hypercalciuria." (PMID 32219087, 2020). "The suppressed PTH and this overloaded blood calcium is urine excreted, causing hypercalciuria − 24-hour urinary levels of calcium above 300mg/dL." (PMID 31851454, 2020). "The current approach is to reduce the serum level of PTH to the upper portion of the reference range to avoid suppression of PTH, which can be associated with hypercalciuria and renal calcification." (PMID 29959430, 2018). "If the hypercalciuria in cadmium-exposed subjects were attributed entirely to excessive calcium loss in the renal tubules, one would expect instead an increase in PTH with higher exposure to compensate for the urinary calcium loss." (PMID 18560534, 2008). "Burosumab improves phosphate homeostasis in children with XLH, but a minority may develop hypercalciuria and nephrocalcinosis, potentially linked to PTH suppression." (PMID 41035763, 2025). "Hypercalciuria, a hallmark of calcium-based nephrolithiasis, can lead to an increase in parathyroid hormone to maintain calcaemia, often resulting in increased bone resorption, which depletes skeletal calcium stores and reduces BMD, especially in weight-bearing areas such as the hip." (PMID 40921881, 2025). "In addition, hyperthyroidism is commonly associated with hypercalciuria, but parathyroid hormone (PTH) levels are usually normal or low." (PMID 34022862, 2021). "Therefore, cluster analysis suggested a continuum of PTH-dependent alterations in mineral metabolic parameters associated with hypercalciuria in postmenopausal women with reduced bone mineral density." (PMID 34977081, 2021). "TransCon PTH may also positively impact hypercalciuria, a major cause of morbidity in patients with HP." (PMID 32212275, 2020). "Persistently elevated levels of PTH may lead to hyperparathyroid bone disease, while suppressed levels of PTH are usually associated with hypercalciuria." (PMID 32596195, 2020). "It is thought that the hypercalciuria may be caused by intestinal hyperabsorption of calcium induced by vitamin D intoxication and decreased reabsorption of tubular calcium induced by low levels of PTH." (PMID 32155322, 2020). "Biochemical abnormalities were found in five patients: one displayed transient hypercalciuria, two had increased levels of urinary N-telopeptide, one was 25 (OH) vitamin D deficient (defined by a 25 (OH) vitamin D level of 22 ng/mL) and one had a moderate but transient increase in PTH (120 pg/mL)." (PMID 23418950, 2013). "Laboratory evaluation revealed markedly elevated serum calcium levels (up to 4.73 mmol/L), hypercalciuria, and suppressed PTH concentrations in both cases." (PMID 41982776, 2026). "The failure to achieve therapeutic targets and persistent hypercalciuria are the main indications for considering therapy with recombinant human parathyroid hormone (rhPTH)." (PMID 41891992, 2026).